PABPC1 (poly(A) binding protein cytoplasmic 1)
Description:
Binds the poly(A) tail of mRNA, including that of its own transcript, and regulates processes of mRNA metabolism such as pre-mRNA splicing and mRNA stability. Its function in translational initiation regulation can either be enhanced by PAIP1 or repressed by PAIP2. Can probably bind to cytoplasmic RNA sequences other than poly(A) in vivo. Binds to N6-methyladenosine (m6A)-containing mRNAs and contributes to MYC stability by binding to m6A-containing MYC mRNAs. Involved in translationally coupled mRNA turnover. Implicated with other RNA-binding proteins in the cytoplasmic deadenylation/translational and decay interplay of the FOS mRNA mediated by the major coding-region determinant of instability (mCRD) domain. Involved in regulation of nonsense-mediated decay (NMD) of mRNAs containing premature stop codons; for the recognition of premature termination codons (PTC) and initiation of NMD a competitive interaction between UPF1 and PABPC1 with the ribosome-bound release factors is proposed. By binding to long poly(A) tails, may protect them from uridylation by ZCCHC6/ZCCHC11 and hence contribute to mRNA stability. (Microbial infection) Positively regulates the replication of dengue virus (DENV).
Synonyms: PAB1; PABP; PABP1; PABPC2; PABPL1
Tractability: Small molecule: a structure with a bound ligand is known; a high-quality ligand is known. PROTAC: ubiquitination databases record sites on it; its protein half-life has been measured; a small molecule that binds it is known.
Gene: Protein-coding gene on chromosome 8 (100,685,816 to 100,722,809, reverse strand). Ensembl gene ENSG00000070756.
Subcellular location: Cytoplasm; Cytoplasm, Stress granule; Nucleus; Cell projection, lamellipodium
Subcellular location (Human Protein Atlas): Cytosol
Pathways (Reactome):
Metabolism of RNA: AUF1 (hnRNP D0) binds and destabilizes mRNA; Deadenylation of mRNA; Nonsense Mediated Decay (NMD) enhanced by the Exon Junction Complex (EJC); Nonsense Mediated Decay (NMD) independent of the Exon Junction Complex (EJC)
Developmental Biology: M-decay: degradation of maternal mRNAs by maternally stored factors; Regulation of expression of SLITs and ROBOs; Z-decay: degradation of maternal mRNAs by zygotically expressed factors
Metabolism of proteins: L13a-mediated translational silencing of Ceruloplasmin expression; Translation initiation complex formation
Disease: Dengue Virus Genome Translation and Replication
Gene Ontology:
Molecular function: mRNA 3'-UTR binding; mRNA binding; poly(A) binding; poly(U) RNA binding; protein binding; RNA binding; translation activator activity; nucleic acid binding
Biological process: CRD-mediated mRNA stabilization; negative regulation of nuclear-transcribed mRNA catabolic process, deadenylation-dependent decay; negative regulation of nuclear-transcribed mRNA catabolic process, nonsense-mediated decay; positive regulation of cytoplasmic translation; positive regulation of viral genome replication; mRNA splicing, via spliceosome; mRNA stabilization; positive regulation of nuclear-transcribed mRNA catabolic process, deadenylation-dependent decay; positive regulation of nuclear-transcribed mRNA poly(A) tail shortening; regulatory ncRNA-mediated gene silencing
Cellular component: catalytic step 2 spliceosome; cell leading edge; cytoplasm; cytoplasmic ribonucleoprotein granule; cytoplasmic stress granule; cytosol; extracellular exosome; focal adhesion; mCRD-mediated mRNA stability complex; membrane; nucleus; ribonucleoprotein complex; lamellipodium
Genetic constraint (gnomAD): Loss-of-function variants: 2 observed, 52.84 expected, observed/expected ratio (o/e) 0.0378, 90% interval 0.014 to 0.12. The upper end of that interval is the gene's LOEUF score, 0.12, which puts it in group 1 of 6, group 1 being the genes least tolerant of losing a copy. Missense variants: 245 observed, 698 expected, observed/expected ratio (o/e) 0.35, 90% interval 0.31 to 0.39. Synonymous variants: 212 observed, 226.6 expected, observed/expected ratio (o/e) 0.94, 90% interval 0.84 to 1.05.
Homologues: Orthologues: chimpanzee PABPC1 (100% identical), dog PABPC1 (100% identical), macaque PABPC1 (100% identical), pig PABPC1 (99% identical), guinea pig PABPC1 (91% identical), rat Pabpc6 (83% identical), mouse Pabpc6 (82% identical), mouse Pabpc2 (81% identical), rat Pabpc2 (75% identical). Paralogues in human: PABPC3 (92% identical), PABPC4 (78% identical), PABPC1L (68% identical), PABPC4L (42% identical), PABPC5 (38% identical), PABPC1L2A (25% identical), PABPC1L2B (25% identical), RBMS3 (18% identical), RBMS1 (18% identical), RBMS2 (17% identical), PUF60 (16% identical), SYNCRIP (16% identical), and 12 more.
Diseases named in the same sentence as PABPC1 in open-access papers:
PABPC1 is named in the same sentence as 87 diseases in open-access papers, as found by Europe PMC text mining. Sharing a sentence is not in itself a finding about the gene and the disease. The quoted sentences say what the papers report.
viral infection (27 papers, 2011 to 2026). "To compare RNase L activation, we counted infected cells (dsRNA-positive) from 15 distinct IFA views for each viral infection and calculated the percentage of infected cells exhibiting PABPC1 cytoplasmic puncta or nuclear translocation." (PMID 40838727, 2025). "In the context of viral infections, PABPC1 has been reported to be degraded or suppress other host proteins in viral infections." (PMID 39338982, 2024). "On the other hand, we observed induction of PABPC1+ SG formation in SeVeGFP-infected NSPHs, highlighting a clear difference between the two viral infections in terms of the types of SGs induced in the NSPH model." (PMID 39351233, 2024). "We propose that the roles of A3B and PABPC1 during viral infection are to ensure the proper activation of PKR and translation shutdown in the presence of viral RNAs by counterbalancing ADAR1’s inhibition of PKR activity." (PMID 36781883, 2023). "Herein, we identified a new complex formed between A3B and PABPC1 that is essential to induce PKR activity during viral infection." (PMID 36781883, 2023). "We propose that A3B, in addition to its canonical role to edit viral genomes, functions with PABPC1 as important innate immunity mediators, protecting cells at different steps of the innate immune response against viral infections." (PMID 36781883, 2023). "PABPC1 is a nucleocytoplasmic shuttling protein, and its subcellular distribution can be altered dynamically in response to cellular stress or viral infection." (PMID 36614257, 2023). "Among the proteins that showed a greater enrichment in the tRF5-GluCTC complex compared to scrambled oligos (fold enrichment ≥10), we selected poly(A)-binding protein cytoplasmic 1 (PABPC1) as the primary target of our studies due to its known involvement in other viral infections." (PMID 39338982, 2024). "As mentioned, PABPC1 plays a role in several viral infections." (PMID 39338982, 2024). "PABPC1 was selected for experimental confirmation due to its reported role in viral infections." (PMID 39338982, 2024). "In addition to the role of PABPC1 in mediating RNA synthesis, PABPC1 has also been reported to interact with virus proteins to control viral infections." (PMID 39338982, 2024). "Arising from the observation that PABPC1 is essential for the formation of SeV-induced SGs, we then hypothesized that the PABPC1-A3B complex may play an important role in promoting the signaling events required for SG formation during viral infection." (PMID 36781883, 2023). "Thus, similar to viral infection, PABPC1 relocalization occurs coincidentally with increased mRNA decay and transcriptional repression in the context of early apoptosis." (PMID 34085923, 2021). "The results reveal the diverse functions of PABPC1 during different viruses infection." (PMID 32512928, 2020). "Puromycin labeling revealed a marked decrease in mRNA translation upon PABPC1 or LARP1 knockdown, mirroring the effects of viral infection." (PMID 40294010, 2025). "While the W187R substitution in NS1 did not affect nuclear PABPC1 accumulation, which was comparable to WT PR8 virus infection, NS1(123,124A) mutant virus did not cause this phenotype." (PMID 38629840, 2024). "Thus, the multi-protein complex, consisting of A3B, PABPC1, DDX3, and MOV10 is pre-formed in cells and relocates to SGs after viral infection." (PMID 36781883, 2023). "However, this hyperadenylation was not driven by nuclear PABPC1 which does not occur in PR8-NS1(N80) mutant virus infection." (PMID 38629840, 2024). "Thus, PABPC1 inhibition by viruses could also be vital to limit PKR activation and translation arrest during viral infections." (PMID 36781883, 2023). "Despite the vhs-GFP retaining activity in transient transfection, it failed to induce mRNA degradation or PABPC1 relocalization to the nucleus in the context of virus infection, whereas PKR phosphorylation was enhanced, suggesting that vhs enzymatic activity was abrogated in this virus." (PMID 35758691, 2022).
viral infection (continued). "The lack of PABPC1 relocalization to the nucleus raised the possibility that vhs may not be active as an endoribonuclease when expressed in the context of virus infection." (PMID 35758691, 2022). "We have not found any particular relation between them; however, some of them might play a role in processes such as protein synthesis regulation in cardiomyocytes (PABPC1), cardiac differentiation and development (FURIN; ADAR), or cellular response to viral infection (TMED2)." (PMID 33917391, 2021). "Aspects of viral infection that downregulate host gene expression, such as host shutoff and PABPC1 re-localization, do not require PAN RNA, but instead affect the expression level of PAN RNA itself both in transiently transfected cells and in bona fide infected cells." (PMID 22022268, 2011). "Surprisingly, in the absence of PABPC1, the formation of G3BP1 foci was abrogated in SeV-infected cells but not after arsenite treatment or poly(I:C) transfection, suggesting that PABPC1 has another important function in promoting SG formation exclusively during viral infection." (PMID 36781883, 2023).
gastric cancer (15 papers, 2018 to 2026). A primary or metastatic malignant neoplasm involving the stomach. "Compelling evidence demonstrates that PABPC1 knockdown suppresses gastric cancer cell proliferation and promotes apoptosis." (PMID 37506150, 2023). "PABPC1 has been shown to be an oncogene that is upregulated in gastric carcinoma, where high expression predicts poor survival." (PMID 37296477, 2023). "PABPC1 regulates the proliferation and transformation of gastric cancer cells in vitro and in vivo, and is also directly involved in breast carcinogenesis by affecting chemoresistance." (PMID 36531055, 2022). "further demonstrated that PABPC1 knockdown induced apoptosis in gastric cancer cells through upregulation of pro-apoptotic and downregulation of anti-apoptotic proteins, and that miR-34c was a target of PABPC1." (PMID 36531055, 2022). "It was also reported that PABPC1 plays a carcinogenic role by inhibiting the expression of miR-34c in gastric carcinoma." (PMID 34027108, 2021). "PABPC1 promotes growth and progression of gastric cancer cells by regulating miR-34c and induces proliferation of hepatocellular carcinoma cells by promoting entry into the S phase." (PMID 33584809, 2020). "In gastric cancer, METTL3 interacts with poly(A) binding protein cytoplasmic 1 (PABPC1) and stabilizes its association with the cap-binding complex eukaryotic translation initiation factor 4F (eIF4F), whereas METTL16 directly interacts with the translation repressor eIF4E2 in lung cancer." (PMID 41459114, 2026). "Similarly, in gastric cancer, CircPTK2 interacts with the PABPC1 protein in bladder cancer (BCa) cells." (PMID 40130381, 2025). "The research indicated that PABPC1 induced carcinogenesis in gastric cancer by regulating miR‐34c." (PMID 37506150, 2023). "As reported, highly expressed PABPC1 was observed in gastric carcinoma tissues and could predict poor survival, while downregulation of PABPC1 could induce apoptosis." (PMID 34027108, 2021). "However, high level expression of FOXC2 and PABPC1 in gastric cancer as well as in the activation of epithelial mesenchymal transition (EMT) and metastasis by overexpression of FOXC2 in cancer cells are potentially consistent with their role in suppressing the p16INK4a-dependent senescence." (PMID 34634809, 2022). "Similarly, PABPC1 depletion in gastric cancer cells BGC823, MKN-45 and MGC803 reduced cell proliferation rate and colony-forming activity, and tumor xenografting assays suggested that PABPC1 knockdown significantly inhibited gastric cancer growth in vivo." (PMID 36531055, 2022).
bladder cancer (14 papers, 2020 to 2025). "In bladder cancer, circPTK2 binds to PABPC1 and stabilizes SETDB1 mRNA to promote its expression, facilitating SETDB1‐mediated EMT and gemcitabine resistance." (PMID 39901896, 2025). "Mechanistically, PABPC1 mainly is regulated by noncoding RNAs, such as circPTK2 in bladder cancer and lncRNA SNHG14 in HCC." (PMID 37581938, 2023). "Additionally, in bladder cancer, PABPC1 enhances cell migration, invasion, and gemcitabine resistance through the PTK2-SETDB1 pathway." (PMID 41249135, 2025). "PABPC1 promotes proliferation and migration in bladder cancer by stabilizing the lncRNA PAGBC29." (PMID 32527996, 2020). "In bladder cancer, circSTX6 increases the expression of SUZ12 by sponging miR‐515‐3p and interacting with the mRNA stabilizer PABPC1, enhancing the chemoresistance of bladder cancer cells to cisplatin by facilitating DNA damage repair and inhibiting apoptosis." (PMID 39901896, 2025). "For example, circPTK2 binds to PABPC1 and enhances its ability to stabilize SETDB1 mRNA, thus promoting tumor metastasis and gemcitabine resistance in bladder cancer." (PMID 39143552, 2024). "In bladder cancer, circPTK2 enhances the stability of SETDB1 mRNA by binding to PABPC1, subsequently facilitating SETDB1 expression." (PMID 38664370, 2024). "Additionally, CircPTK2 interacts with PABPC1 and enhances SETDB1 mRNA expression, thereby facilitating gemcitabine resistance in bladder cancer." (PMID 39866227, 2025). "Additionally, circPTK2 can bind to PABPC1 and stabilize SETDB1 mRNA, thereby promoting SETDB1 expression, EMT, and metastasis in bladder cancer." (PMID 40612865, 2025). "CircPTK2/PABPC1/SETDB1 pathway promotes metastasis and gemcitabine resistance of bladder cancer." (PMID 38664370, 2024).
breast carcinoma (14 papers, 2018 to 2025). "Poly(A) binding protein cytoplasmic 1 (PABPC1), which is involved in mRNA regulation and stability, is upregulated in several types of cancer including breast cancer and is associated with a poor prognosis." (PMID 40900789, 2025). "In scientific publications, we can find confirmation that SNHG14 lncRNA promotes breast cancer and Trastuzumab resistance by regulating PABPC1 expression through H3K27 acetylation." (PMID 38338997, 2024). "Scientific publications confirm that lncRNA SNHG14 promotes breast cancer tumorigenesis and Trastuzumab resistance by regulating PABPC1 expression through H3K27 acetylation." (PMID 38338997, 2024). "In the TCGA database, the transcript level of PABPC1 was positively correlated with that of Mtdh in breast cancer tissues (p ~ 0), while this correlation was weakened in control tissues (p = 0.56)." (PMID 36923539, 2023). "This study presents the tumor-suppressive action of AMPK-inhibited PBMC/lymphocyte-derived CM and evaluates the role of ENO1/MSN-Mtdh regulatory axis as well as PABPC1 in suppressing the progression of breast cancer." (PMID 36923539, 2023). "The following genes were reported to be lower expressed in breast cancer samples of cases compared to controls in two different studies but were reported to be higher expressed in another study: PABPC1, ARPC1A, TXN, TOB1." (PMID 36627894, 2022). "A recent study illustrated that SNHG14 promotes proliferation, invasion, and trastuzumab resistance via modulating poly(A) binding protein cytoplasmic 1 (PABPC1) expression through H3K27 acetylation in breast cancer cells." (PMID 32811821, 2020). "For example, long non-coding RNA SNHG14 induced breast cancer cell trastuzumab resistance by regulating PABPC1 expression through H3K27 acetylation." (PMID 30733855, 2019). "In this study, we has been suggested that lncRNA SNHG14 regulated breast cancer progression and resistance via regulating PABPC1 expression through H3K27 acetylation." (PMID 30063126, 2018). "As expected, we confirmed that PABPC1 was essential for SNHG14‐induced breast cancer tumorigenesis and trastuzumab resistance." (PMID 30063126, 2018). "We identified that PABPC1 was highly enriched with H3K27ac at the promoter of PABPC1 in breast cancer tissues." (PMID 30063126, 2018). "Collectively, we draw a conclusion that lncRNA SNHG14 regulates PABPC1 expression in breast cancer via modulation of H3K27 acetylation at promoter of PABPC1." (PMID 30063126, 2018). "To this end, we validated that the Nrf2 pathway is responsible for the SNHG14/PABPC1‐induced breast cancer progression." (PMID 30063126, 2018). "Our own date showed that SNHG14 promoted breast cancer tumorigenesis and chemo‐resistance via activating PABPC1 through H3K27 acetylation." (PMID 30063126, 2018). "In breast cancer, studies have indicated that PABPC1 mediates SNHG14-induced oncogenic effects." (PMID 34151731, 2021). "To conclude, lncRNA SNHG14 may promote breast cancer progression and trastuzumab resistance via binding to PABPC1 gene." (PMID 30063126, 2018). "Overexpression of SNHG14 promoted the level of PABPC1 in either 1% Tween‐80 or trastuzumab treatment group (Group II vs Group I or Group III vs Group IV, respectively), indicating that SNHG14 regulates breast cancer carcinogenesis and trastuzumab resistance via targeting PABPC1." (PMID 30063126, 2018). "Similarly, there is just a report in breast cancer that the high expression of PABPC1 would promote cancer tumorigenesis and resistance and in lung adenocarcinoma, it might be involved in tumor development." (PMID 32454908, 2020). "Particularly, PABPC1 presented the second highest reduction in the MTT assay next to small nuclear ribonucleoprotein polypeptide E (SNRPE), and its transcript level was elevated in many cancer types including breast cancer." (PMID 36923539, 2023).
breast carcinoma (continued). "Furthermore, in MDA-MB-231 as well as MDA-MB-436 and MCF-7 breast cancer cells, the MTT-based viability was increased by the overexpression of PABPC1 and reduced by the silencing of PABPC1." (PMID 36923539, 2023). "To further investigate whether lncRNA SNHG14 regulates the H3K27 acetylation at PABPC1 promoter, we sublocated the expression of SNHG14 in breast cancer cells." (PMID 30063126, 2018). "Abnormal expression and function of PABPC1 have been detected in gliomas and hepatocellular carcinoma, where PABPC1 is highly expressed and enhances tumor cell proliferation, although the combination of PABPC1 and BRCA1 has been suggested to have an anti-cancer function in breast cancer." (PMID 35346324, 2022).